CD86 (CD86 molecule)
Diseases named in the same sentence as CD86 in open-access papers (continued):
Sharing a sentence is not in itself a finding about the gene and the disease.
tumor (continued). "In addition, mTOR expression was higher in DLBCL than non-tumor control samples, and in tumors, mTOR expression was higher in CD86+ cells in the peri-T area." (PMID 41415285, 2025). "The overexpression of CTLA-4 by iTregs, which, upon interaction with CD80/CD86 on dendritic cells, could suppress T lymphocyte activation or induce anergy in effector T cells, thereby diminishing anti-tumor immunity." (PMID 41203944, 2025). "qPCR analysis of the dissociated tumour tissues showed that the delivery of Il‐12 minicircle‐loaded RBCEVs promoted the up‐regulation of pro‐inflammatory Ifng, Il‐1b and co‐stimulatory signal Cd86 in the tumours." (PMID 39193804, 2025). "Additionally, subgroup analysis revealed a significantly higher CD86 expression in the tumor nests of metastases from HR+/HER2- tumors (p = 0.031)." (PMID 40510346, 2025). "Notably, COF‐loaded reuterin treatment significantly increased the proportion of CD86+ (M1‐like) macrophages while decreasing CD206+ (M2‐like) macrophages within the tumor microenvironment, indicating a shift toward a proinflammatory macrophage phenotype." (PMID 40587842, 2025). "The importance of Smad3 in monocytic development was first highlighted by the increased frequency of CD11b+Ly6Clo cells (with higher CD86 expression) and fewer CD11b+Ly6G+ granulocytic cells in tumor-free mice overexpressing Smad3 in myeloid cells (Lys2-Smad3-AAV9)." (PMID 41360769, 2025). "Moreover, we further immunostained tumor tissues with CD86 and CD206, and the results were fully consistent with our previous findings that treatment with NaHS led to a decrease in CD206 and an increase in CD86 in tumor tissues obtained from BC‐bearing mice." (PMID 39755930, 2025). "Higher CD8+ tumor-infiltrating lymphocyte (TIL) density is associated with pelvic lymph node metastasis, whereas recurrent disease shows enrichment of CD8+ T cells, CD80+CD86+ and CD163+CD206+ macrophages, and FOXP3+CD25+ Tregs." (PMID 40808954, 2025). "Additionally, flow cytometric analysis of mature dendritic cells (identified as CD80+/CD86+ within the CD11c+ cells) from tumor-draining lymph nodes revealed that these DCs effectively home to the tumor-draining lymph nodes and undergo maturation." (PMID 40761260, 2025). "The numbers of CD86+ macrophages (M1‐like) remained largely unchanged, indicating a selective depletion or reprogramming of the M2‐like immunosuppressive tumor‐associated macrophages (TAMs) population rather than a broad suppression of all macrophage subsets." (PMID 40974370, 2025). "In the tumor infiltrating myeloid panel we use CD86 as a marker of M1-like vs. M2-like macrophages." (PMID 39823235, 2025). "The evaluation of the ratio of CD80 and CD86 may serve as a tool for future research in canine neoplasia." (PMID 40271486, 2025). "Similarly, B7 ligands B7-1 (CD80) and B7-2 (CD86) on tumor cells engage CTLA-4 on activated CD8+ T cells, outcompeting CD28 and thereby blocking co-stimulatory signals required for T cell activation, leading to CD8+ T cell anergy." (PMID 41268548, 2025). "The AMPK pathway counteracts mTOR signaling, with AMPK activation in tumor-associated DCs typically inducing tolerogenic properties characterized by improved mitochondrial function, increased FAO and OXPHOS, and diminished CD80/CD86 expression." (PMID 40924040, 2025). "As CD86 and HLA-DR are two markers that are expressed by anti-tumor M1 macrophages, their expression was at first appraised in M2c, in “M2c > M1”-switched, and in M1 control macrophages, to confirm that the expression of these markers was higher in M1 than in M2c." (PMID 40362536, 2025). "The discrepancy between trends shown by our results and known effect of rs1129055 on immune system activation may be also explained by the expression of CD86 by ALK-positive ALCL tumor cells." (PMID 41469691, 2025).
tumor (continued). "Also, in the same study the authors concluded that tumor associated B cells contained a higher percentage of CD19+, CD20+ and CD86+ B cells than in peripheral blood or even healthy controls (p < 0.005)." (PMID 41008839, 2025). "Additionally, we observed a significant increase in IL‐1β and CD86 levels, indicating a shift towards a pro‐inflammatory tumour microenvironment that enhances immune‐mediated killing of cancer cells." (PMID 39193804, 2025). "Furthermore, CD86 in the tumor nest correlated with higher tumor grading, indicating unfavorable properties of CD86." (PMID 40510346, 2025). "Interestingly, here, we observed that both viruses increased DCs, and the expression of the co-stimulatory molecule CD86 on DCs in tumor tissues on day 6 after the first treatment, and VVL-TD-RFP significantly enhanced this response." (PMID 40350204, 2025). "For instance, a recent study indicates that a subset of neutrophils displaying antigen-presenting markers such as HLA-DR, CD80, and CD86 can transport tumor antigens into TDLNs during early stages of head and neck cancer, thereby initiating a tumor-specific immune response." (PMID 40549016, 2025). "Strikingly, untreated A375s yield HMDMs exhibiting a tumor-associated macrophage phenotype characterized by CD40, CD80, and CD206 surface expression while injured A375s yield HMDMs with markers of increased antigen presentation, namely HLADR and CD86." (PMID 40539073, 2025). "This could be attributed to the crucial involvement of C4 CD86+ Memory B cells in the proliferation and differentiation of tumor cells, which occurs through the CD46-JAG1 signaling pathway." (PMID 39744570, 2025). "The main ligands of CTLA-4 are CD80 and CD86, which are expressed on both APCs and tumor cells." (PMID 38791528, 2024). "CTLA-4 is thought to be expressed only on T cells, CD80 and CD86 mainly localizing to cell membranes and rarely expressing in tumor interstitium, are expressed in activated B lymphocytes, activated T lymphocytes, macrophages, peripheral blood mononuclear cells, and DCs." (PMID 39120585, 2024). "Thus, in the TC-1 tumor setting, CD86 is the selective CD28 ligand that supports the generation of an eTreg response after RT." (PMID 38349740, 2024). "For example, differential expression of CD80 and CD86 may correspond with disease progression and prognosis in tumor cells of hematogenic origin." (PMID 39619201, 2024). "In addition to suppressing tumor growth in mouse cancer models, T-Dxd activated dendritic cell maturation through the upregulation of CD86 and major MHC-II expression, along with the increased expression of PD-L1 and MHC class I expression on tumor cells." (PMID 39123362, 2024). "This may be due to chemotherapy activating endogenous anti-tumor immune responses, leading to increased expression of co-stimulatory molecules CD80 and CD86 and downregulation of PD-L1, inducing immunogenic tumor cell death." (PMID 39072331, 2024). "Additionally, there was a significant increase in the proportion of CD80+ and CD86+ dendritic cells (DCs) within mouse tumor tissues after sgPik3cg-DHP/DGA-NVs treatment, indicating DC activation." (PMID 38296939, 2024). "Moreover, CD80 and CD86 expression was upregulated on Kaede-red versus Kaede-green tumour CCR7+ DCs, with expression levels on tumour Kaede-green CCR7+ DCs similar to migrated CCR7+ DCs in matched dLNs." (PMID 38267413, 2024). "Finally, a CD86‐P2A‐EGR3 recombinant mRNA vaccine is developed which leads to tumor control through forced cell differentiation and enhanced immune infiltration." (PMID 38973154, 2024). "This includes whether CCH regression involves increased expression of CD80 and CD86, two well established markers of DC maturation, by tumor cells." (PMID 39619201, 2024). "They raise the possibility that the CD28 ligands CD80 and/or CD86 may dictate Treg numbers after RT in the TC-1 tumor model." (PMID 38349740, 2024).
tumor (continued). "Thus, the expression of CD86 on APCs can contribute both to the promotion and the inhibition of tumor growth." (PMID 38791312, 2024). "In the post-treatment tissues, pCR patients had less CD86 + cell infiltration, whereas higher CD86 + cell density was significantly associated with higher tumor regression grades (TRG) in non-pCR patients." (PMID 38802821, 2024). "Additionally, in the in vivo experiments, increases in CD68+/CD80+ and CD68+/CD86+ cells around the tumor region imply that Nb‐TriTE attracts or activates macrophages (particularly M1) or dendritic cells." (PMID 39234811, 2024). "However, when TGF-β signaling is inhibited, the suppressed expression of MHC II, CD40, CD80, and CD86 on DCs by tumor supernatant is substantially attenuated." (PMID 38164187, 2024). "In addition, overexpression of YAP1 induces the polarization of macrophages into the M2 phenotypes (tumor-associated macrophages) by regulating different genes such as iNOS, MerTK, IL-10, STAT3, CD163, CD206, Arg-1, CD86, and TNF-α in the naive macrophages." (PMID 39630608, 2024). "To further confirm this, we performed immunohistochemical (IHC) staining for the pan-macrophage marker CD68 19, M1-like and M2b-like macrophage markers CD86 20, M2a-like macrophage marker CD206, and M2c-like macrophage marker CD163 21-23 in serial histological sections of EBV-associated tumours." (PMID 39267775, 2024). "Thus, the presence and role of CD86 in the tumor microenvironment, as well as the PD-L1 marker, prove to be complex and can vary, depending on the type of cancer and the immunological status of the tumor." (PMID 38791312, 2024). "The mature dendritic cells (CD11c+CD80+CD86+, DCs) in tumor tissues was firstly examined." (PMID 39494618, 2024). "Furthermore, MFI of CD80 and CD86, and percentage CD86+ cells were low on these cells before co-culture with transfected tumor cells confirming that at this stage cells were immature DC (iDC)." (PMID 39007281, 2024). "Additionally, immunofluorescence results showed that inosine markedly increased the expression of F4/80+CD86, an M1 macrophage marker, in tumor tissues." (PMID 39795180, 2024). "Tumor DCs expressed similar levels of CD86 and PD-L1 in NcDasecKO mice compared with WT mice." (PMID 38302493, 2024). "Moreover, interactions between immune checkpoints and their ligands (e.g., PD-1/PD-L1 and CTLA-4/CD86) are further involved in the metabolic reprogramming of tumor cells and immune cells." (PMID 38361757, 2024). "Our results showed that innate immune training on DCs induced by CTB promoted robust recruitment of these cells at the stimulation site and tumor tissue, with higher expression of CD86, which could directly impact CD8 T cell phenotype." (PMID 38812523, 2024). "RT-qPCR results indicated a significant upregulation in the expression of M2 macrophage markers (MRC1, CD163) within HCC-conditioned TAMs, while the expression levels of M1 markers (CD86, iNOS) remained unchanged, suggesting a skew towards M2 polarization in the tumor microenvironment." (PMID 38938448, 2024). "Finally, higher levels of mature DCs (CD11c+CD80+CD86+) in the tumor draining LNs and CD8+ cytotoxic T cells in untreated distant tumors were recorded." (PMID 38803496, 2024). "On the other hand, the control of tumor growth could be a result of a proper antitumoral response from T cells elicited by CTB-trained DCs with high expression of CD86." (PMID 38812523, 2024). "Therefore, the aim of this study is to analyze the TME of cSCC and BCC by tissue microarray (TMA) immunohistochemistry (IHC) for PD-1, PD-L1, CD28, and CD86 expression in the invasive front as well as in the core of both tumor entities." (PMID 39329753, 2024). "MFI of CD80 and CD86 were increased upon co-culture with 1B3-transfected tumor cells compared to co-culture with mock transfected tumor cells, but the effect was not as strong as when cells were stimulated with a cytokine cocktail known to induce DC maturation." (PMID 39007281, 2024).
tumor (continued). "We next assessed how inhibition of PD-1 and/or CD86 affected RT-induced tumor control." (PMID 38349740, 2024). "This secretion of interferon-gamma (IFN-γ) can prompt cancer cells to increase the expression levels of Major Histocompatibility Complex-I (MHC-I) and CD86.Ultimately, this upregulated expression of MHC-I and CD86 can enhance T-cell-mediated anti-tumor immune responses." (PMID 39655080, 2024). "In addition, IHC staining of tumor sections showed that exosomal lncRNA HAGLROS-treated THP-1 cells significantly decreased the expression of CD86 in tumor tissues, while increasing the expression of CD206." (PMID 39198393, 2024). "Within tumours, there was also a trend of an increase in CD86 MFI in APCs." (PMID 38554167, 2024). "Furthermore, cellular expression of CD80 and CD86 in each of the three layers was compared between the three tumor stages, respectively." (PMID 39619201, 2024). "Thus, in the TC-1 model, RT-induced CTL priming was likely increased upon CD86 blockade by increasing the frequency and costimulatory state of migratory cDC1s that present tumor antigen in the TdLN." (PMID 38349740, 2024). "Finally, although not significant, in progression-free subjects—CD8+ CD28+ PD-1+ T cells were in closer proximity to both APCs (CD11c+ CD86+) and tumor cells (CK+) especially in the tumor-surrounding stroma, compared to PD." (PMID 37349318, 2023). "Interestingly, unlike in the case of macrophages, the combination CpG-STAT3ASO/anti-PD-1 treatment but not CpG-STAT3ASO or anti-PD-1 alone led to a significant recruitment of activated (MHC-IIHI and CD86+ or CD80+) DCs into tumor-draining lymph nodes." (PMID 38259453, 2023). "Interestingly, in the stroma, CD8+CD28+PD-1+ T cells were also found to be closer to both tumor cells and to CD11c+CD86+ APCs in progression-free patients." (PMID 37349318, 2023). "Interestingly, the results show that there is a decreased expression of the co-stimulatory CD86 marker in both iDCs and mDCs in the presence of the PDTOs, suggesting a tumor-induced immunosuppressive effect." (PMID 36761758, 2023). "Furthermore, the tumours that have normal expression of MHC molecules often lack co-stimulatory molecules such as CD80 or CD86, which abrogates the activation of T lymphocytes." (PMID 37631324, 2023). "Thus, the immunosuppressive TAMs expressing PD-L1 and possibly CD86 are more frequently found in the close vicinity of tumor HRS cells." (PMID 37372147, 2023). "Interestingly, data from early lung adenocarcinoma showed that tumour-associated macrophages (TAMs) expressed the immunomodulatory transcription factor PPARγ, CD64, CD14, and CD11c and had reduced expression of CD86 and CD206." (PMID 39698297, 2023). "Regarding HGG, CD86 was significantly upregulated in tumor tissues (P<0.001)." (PMID 38154107, 2023). "They utilized a charge-altering releasable transporter mRNA delivery platform to induce the local expression of cytokines (CD70, IL-12, and IFN-γ) and costimulators (OX40L, CD80, and CD86) individually and in combination in two tumor models (A20B-cell lymphoma and CT26 colon carcinoma)." (PMID 36839944, 2023). "For example, studies have demonstrated that tumor-infiltrating DCs exhibit decreased expression of co-stimulatory molecules such as CD86 and CD80, while concurrently displaying heightened expression of immune inhibitory molecules such as programmed cell death 1 ligand 1 (PD-L1)." (PMID 38012715, 2023). "Other co-stimulatory molecules OX-40L/CD80/CD86 could be delivered by LNPs and activate APCs and T cells, which produced an immune-active state in the tumor microenvironment." (PMID 37805495, 2023). "Similarly, the upregulation of CCR7, XCR1, MHC-II molecules and CD86 on cDC1 was observed upon BCL2 inhibition with venetoclax in the MCA205 tumor model." (PMID 37623817, 2023).
tumor (continued). "Therefore, we assessed the effect of combination treatment on T-helper lymphocytes (CD4+), cytotoxic lymphocytes (CD8+), activated lymphocytes (Granzyme B+), and antitumor macrophages (CD86 positive M1 type macrophages) infiltrating tumor tissue." (PMID 37640735, 2023). "Moreover, Vacc DCs also upregulated number of DCs that were MHCI + CD86 + CD11c+ in the tumour as compared to other treatment groups, suggesting the Vacc DCs support the activation of DCs in vivo." (PMID 37660049, 2023). "Furthermore, Cd86 was significantly upregulated in the dLN and tumor on day 3, with the addition of CS/IL-12 to CA." (PMID 37190138, 2023). "Dex were found to possess MHC-I and MHC-II antigen-presenting molecules and CD86 costimulatory molecules, which could potentially stimulate T cells and inhibit tumor growth." (PMID 37481646, 2023). "Interestingly, we observed that the exosomes derived from A549-Linc01703 decreased the infiltration of CD86+ B cells in the tumor microenvironment, while CD81 silencing reversed it." (PMID 38136327, 2023). "However, our data demonstrating decreased MHC-I, MHC-II, CD80, and CD86 expression as A20 tumors progress provide additional context to the mechanism of this enhanced anti-tumor response." (PMID 37016127, 2023). "Also, Vacc DCs also upregulated number of DCs that were MHCII + CD86 + CD11c+ in the tumour as compared to adoptively transferred F16BP DCs, suggesting the Vacc DCs skew toward MHCII associated responses in vivo." (PMID 37660049, 2023). "Furthermore, after L. casei & L. reuteri or TAK-242 treatment, the expressions of CD86 and iNOS were increased in tumor tissues, whereas the expressions of CD206 and Arg-1 were decreased at the same time." (PMID 37904102, 2023). "To prove whether this effect relies on tumor-infiltrating macrophages, we determined the percentage of CD86+ and CD206+ macrophages in tumors of the different groups." (PMID 37679802, 2023). "In particular, M1 macrophages are regarded as anti-tumor and typically identified by the surface markers CD86 and CD64, while M2 are polarized macrophages, commonly considered tumor-associated macrophages (TAMs) and typically express the surface markers CD206 and CD163." (PMID 37033265, 2023). "Similarly, multiple pathways implicated in PKD (e.g., IFN-γ/JAK-STAT, TNF-α, NF-κB, PI3K, and HIF-1) drive PD-L1 and CD80/CD86 expression on tumor cells." (PMID 37345660, 2023). "LID + US also significantly increased the percentage of CD80 + DC in the tumor, increased the percentage of CD86 + DC in the tumor-draining lymph nodes, and enhanced the phosphorylation of TBK1 and IRF3, which were related to the activation of STING pathway in the tumor tissue." (PMID 37391428, 2023). "PF and PD displayed similar numbers of CD11c+ CD86+ APCs in the tumor and stroma areas." (PMID 37349318, 2023). "Overall, our results suggest that the expression of co-stimulatory molecules (CD86), antigen presentation machinery (HLA-DR), and co-inhibitory molecules (PD-L1) in DCs, and their ability to activate T cells were impacted upon interaction with tumor organoids." (PMID 36761758, 2023). "However, the combined CpG-STAT3ASO/anti-PD-1 treatment and to a lesser extent CpG-STAT3ASO alone strongly increased the recruitment of activated, antigen-presenting MHC-IIHI/CD86+ macrophages and DCs into tumor-draining lymph nodes." (PMID 38259453, 2023). "Moreover, there was a significant (p < 0.001) 2-fold increase in F4/80+CD86+ cells (M1 macrophages) among F4/80+ cells in US+CA-treated tumours compared to untreated tumours, suggesting a shift in TAM polarisation after treatment." (PMID 37631324, 2023). "Therefore, the maturation of DCs (CD11c+CD80+CD86+) in tumor draining lymph nodes was analyzed by flow cytometry after different treatment." (PMID 37051250, 2023).